CCNC (cyclin C)
Diseases named in the same sentence as CCNC in open-access papers (continued):
Sharing a sentence is not in itself a finding about the gene and the disease.
cancer (continued). "Therefore, cyclin C’s control over mitochondrial dynamics may differ depending on the cancer type examined." (PMID 30621145, 2019). "Consistent with our cell biological study that shows favorable effect of esomeprazole in controlling cancer cell growth, the RPPA data revealed that esomeprazole regulates critical cell cycle proteins such as p21, p300, cyclin C, and ULK1." (PMID 34262645, 2021). "Cyclin C and CDK8 form part of the CDK8 kinase module of the RNAPII mediator complex, and deregulation of either gene has functional consequences for cancer development." (PMID 34329458, 2021). "Examination of alterations in different cancers shows that CDK8, CDK19 and CCNC can be amplified or deleted either independently of each other or in combinations." (PMID 31382571, 2019). "ELOVL7, PTDSS1, POLR1D, TBC1D22A, CCNC and TCF25 are some of the interesting genes with cancer related functions identified from the DES analysis." (PMID 24088394, 2013). "Cancer Cell Line Encyclopedia (CCLE) data analysis showed that RNA expression of CDK8 (but not of CDK19 or CCNC) was significantly higher in TNBC cell lines than in cell lines from other subtypes of BrCa." (PMID 39541354, 2024). "CCNB1IP1, CCNC, CCND2, CDK5R2, CDK9, and GAK were upregulated in all three cancer regions." (PMID 33302383, 2020). "In this section, we outline some of the concepts in targeting Cdk8 for cancer therapy and provide an example of repurposing an already established drug to target the non-transcriptional mode of action of cyclin C." (PMID 30621145, 2019). "Since we were only analyzing one CCNC core from most cancer cases, we did not expect a significant difference in the methylation of benign cores between cases and controls." (PMID 25548652, 2014). "While we cannot rule out that all methylation positive CCNC cores were derived from near cancer lesions, this possibility is highly unlikely since the majority of cores were from repeat biopsies." (PMID 25548652, 2014). "On the other hand, potential target cancers could be identified through informatic analysis of clinical data, which may reveal tumor types where CDK8/19 or their binding partner Cyclin C (CCNC) would be amplified or overexpressed or where CDK8/19 expression would be associated with bad prognosis." (PMID 31382571, 2019). "To identify other cancers where these novel drugs may provide benefit, we queried genomic and transcriptomic databases for potential impact of CDK8, CDK19, or their binding partner CCNC." (PMID 31382571, 2019).
tumor (18 papers, 2015 to 2026). "Mice with ubiquitylation sites point mutations of CCNC (CCNC3KtoR) had comparable tumour size with wild‐type mice under the same condition." (PMID 35343092, 2022). "Deletions of 6q16.2 are frequently found in blood cancers and solid tumors, hinting at a tumor suppressor role for cyclin C." (PMID 40358161, 2025). "Consistent with observations that CDK8 phosphorylation has both positive and negative effects on transcription factors, alterations in the CDK8 and cyclin C (CCNC) genes have been implicated as both oncogenes and tumor suppressors." (PMID 37671866, 2023). "We identified amplifications in oncogenes, including FCGR2B and CCND1, and deletions of tumor suppressors, such as CCNC and RB1, only in HPV-negative tumors." (PMID 37461056, 2023). "Further evidence for a role of cyclin C as a tumor suppressor was demonstrated in organs isolated from thyroid-specific and pancreas-specific (R.S. and Kerry S. Campbell, Fox Chase Cancer Center, Philadelphia, PA unpublished observations) CCNC knockout mouse." (PMID 33418995, 2021). "We have also used cBioPortal to query RNA-Seq data for CDK8, CDK19, and CCNC RNA expression in different tumor types in the TCGA data." (PMID 31382571, 2019). "In contrast to most targets of tumor-suppressive drugs (such as, for example, CDK4/6), very few tumor cell lines showed pronounced dependency on CDK8/CDK19/CCNC in DepMap analysis." (PMID 31382571, 2019). "Cyclin C also plays a tumor suppressor role in anaplastic thyroid tumors." (PMID 40358161, 2025). "Due to their potential ability to stabilize Notch, cyclin C/CDK8/19 inhibitors may be of therapeutic benefit for the hematologic malignancies in which Notch functions as a tumor suppressor such as CML and CMML." (PMID 25914884, 2015). "Therefore, despite the pro-oncogenic effects associated with Cdk8 overexpression, these observations allude to a tumor suppressive role of cyclin C. This inconsistency may be explained by cell-type specific differences in cyclin C-Cdk8 transcriptional control." (PMID 30621145, 2019). "Therefore, cyclin C/CDK3/CDK8/CDK19 complexes function as tumor suppressors in T-ALL by preventing the accumulation of ICN1 and the lack of these complexes led to enhanced T-ALL development in Lck-LMO1 transgenic mice that mimic the alterations found in human T-ALL." (PMID 25914884, 2015). "Through these two genome-wide screens and integration with CRISPR knockout datasets from T cells, MED12, CCNC, and ARIH2 were identified as candidate genes whose knockout enhances the anti-tumor response of NK cells." (PMID 41139700, 2026). "When phosphorylated by CDK3/cyclin-C, RB1 is a major regulator of cell division and works as a tumor suppressor, promoting the G0-G1 transition." (PMID 36531719, 2022). "Other 6q15 genes with potential tumor suppressive functions for example include EEF1A1, ZNF292, SNORD50A, PRDM1, CCNC, FOXO3, WISP3, and FRK." (PMID 34625909, 2022). "In the in vivo studies, xenograft tumour formation in nude mice were conducted in four groups: CCNC–/– + CCNCWT + saline, CCNC–/– + CCNCWT + cisplatin, CCNC–/– + CCNC3ktoR + saline and CCNC–/– + CCNC3ktoR + cisplatin." (PMID 35343092, 2022). "Given that Cyclin C depleted cells had reduced basal levels of DNA:RNA hybrids, correlating with reduced ATRi/CHK1i-induced hybrid formation, it is possible that basal DNA:RNA hybrid levels could be used as a phenotypic biomarker in patient tumour samples to predict ATR and CHK1 inhibitor efficacy." (PMID 34329458, 2021). "Here, we review and discuss the biology of cyclin C, focusing mainly on its transcriptional and non-transcriptional roles in tumor promotion or suppression." (PMID 30621145, 2019). "Therefore, because of the dual role of the cyclin C/CDK8/CDK19 complexes functioning in some tumors as oncogenes and in other tumors as tumor suppressor genes the use of pharmacological inhibitors of this complex should be carefully considered depending on tissue type." (PMID 25914884, 2015).
tumor (continued). "However, in an orthotopic mouse model implanted with PATC148 tumors, only CCNC and ARIH2 double knockout CAR-NK cells—not MED12-knockout CAR-NK cells—were able to significantly reduce tumor burden." (PMID 41139700, 2026).
hematologic malignancies (2 papers, 2015 to 2019). "However, deletions of the genomic locus on chromosome 6 (6q21) harboring the gene encoding cyclin C (CCNC) have been identified in both solid tumors and hematologic malignancies." (PMID 30621145, 2019).
degenerative diseases (1 paper, 2019). "Consistent with the stress signaling role of cyclin C in activating mitochondrial fission and apoptosis, pifithrin-μ could be utilized as a cytoprotective agent in the treatment or prevention of degenerative diseases that are associated with altered mitochondrial dynamics." (PMID 30621145, 2019).
infection (1 paper, 2020). The state of being infected such as from the introduction of a foreign agent such as serum, vaccine, antigenic substance or organism. "Apparent CDK8 levels in the soluble nuclear fraction remained elevated, relative to Cyclin C, throughout the course of infection and were coincident with a progressive increase in the phosphorylated form of a known CDK8 substrate, H3S10-P, relative to total histone H3." (PMID 32560467, 2020).
CCNC also shares sentences with these, for which no sentence is quoted: acute myeloid leukemia (2 papers); colon cancer (2); breast invasive ductal carcinoma (1); cardiovascular disease (1); Cirrhosis (1); colon adenocarcinoma (1); developmental and epileptic encephalopathy, 87 (1); diabetes (1); Insulin resistance (1); liposarcoma (1); lung carcinoma (1); Macular dystrophy (1); North Carolina macular dystrophy (1); osteoporosis (1); pancreatic neoplasm (1); prostate adenocarcinoma (1); prostate carcinoma (1); rectal adenocarcinoma (1); sarcoma (1); stomach adenocarcinoma (1); thyroid cancer (1); tubular stomach adenocarcinoma (1).